CLEC9A (C-type lectin domain containing 9A)
Diseases named in the same sentence as CLEC9A in open-access papers (continued):
Sharing a sentence is not in itself a finding about the gene and the disease.
tumor (continued). "Humanized mouse tumor models suitable to investigate the feasibility, immunogenicity, and therapeutic efficacy of vaccines targeting human Clec9A+ DCs would require the presence of adequate numbers of this critical population of human DCs." (PMID 37626903, 2023). "Rather, an antibody targeting a DC specific surface marker, such as C-type lectin domain containing 9A (Clec9a), is conjugated to a tumor antigen and injected into patients to promote the delivery of immunogenic tumor antigens to key DC subsets." (PMID 37830618, 2023). "The induction of both Axl and Clec9A further suggests that NDV promotes both tumor Ag uptake and cross-presentation of tumor Ag by DCs." (PMID 36418317, 2022). "CLEC9A and CXCR3 are associated with intratumoral dendritic cells (DCs), which are necessary for anti-tumor immunity." (PMID 36583019, 2022). "It appears from the findings of this study that the presence of these clec9a+ DCs is important in the role of tumour-infiltrating CD8 lymphocytes (TILS), as both are expressed at the same time." (PMID 34415004, 2021). "Here, we show that the CLEC9A product, DNGR-1, can promote cross-presentation of dead tumor cell antigens leading to anti-tumor immunity but that this effect is often masked by sGSN produced either locally in the TME or circulating in plasma." (PMID 34081922, 2021). "IR alone and combination therapy increased the percentage of Clec9a+ DCs in tumor tissues as compared with the normal saline control group." (PMID 34158852, 2021). "Although this antibody-based Clec9a delivery system with an adjuvant is a promising strategy for tumor vaccination, there are two concerns." (PMID 34158852, 2021). "As Clec9A promotes CD8+ T cell cross-priming, several in vitro studies have been performed to explore Clec9A targeting to induce anti-tumor immune responses." (PMID 33679806, 2021). "CLEC9A was markedly downregulated in LUAD and associated with prognosis and tumor immune microenvironment of LUAD." (PMID 34616670, 2021). "Four cell types, SELENOP+M4, CXCL9+M2, CD1C+DC1, and CLEC9A+DC2, were negatively associated with tumor progression (FDR < 0.05)." (PMID 34659209, 2021). "In this study, we showed that radiotherapy increased the proportion of Clec9a+ DCs within the tumor and enhanced the therapeutic effects of the CBP-12 conjugated peptide vaccine." (PMID 34158852, 2021). "An increase in tumor-infiltrating Clec9a+ DCs was important for enhancing the immune response in the tumor microenvironment." (PMID 34158852, 2021). "We have recently demonstrated the ability of a nanovaccine containing the Melan A Ag and α-GalCer and coated with anti-CLEC9A Abs to strongly induce the expansion of tumor Ag-specific CD8+ T cells from human PBMCs in vitro." (PMID 32973811, 2020). "Here, using a nanovaccine loaded with the tumor Ag Melan A and α-GalCer and decorated with anti-CLEC9A Abs, we aimed to analyze the immune response in HIS-CD8/NKT mice." (PMID 32973811, 2020). "Animal studies showed that antigen targeting to Clec9A induces strong anti-tumor immunity via the activation of CD8+ and CD4+ T cells." (PMID 32150821, 2020). "We have previously designed a PLGA-based NP vaccine by encapsulating a tumor Ag and α-GalCer and decorating the NPs with Abs against human CLEC9A to target cross-priming CD141+ DCs known to be capable of inducing potent CTL responses." (PMID 32973811, 2020). "Elevated levels of TIDCs have been shown to improve CD8+ T‐cell persistence in tumours, and once expanded, TIDCs can be targeted by Clec9A‐TNE." (PMID 32704371, 2020). "The targeting of CLEC9A with tumor-expressed peptides together with adjuvant was shown to induce efficient cross-priming of CD8+ T cells and to control tumor immunity in a mouse model of melanoma." (PMID 32133013, 2020).
tumor (continued). "Specifically, murine CD8a+CD103+BATF3+CLEC9A+XCR1+ cDC1s have been demonstrated to have a critical role in the cross-presentation of tumor antigens and are generally thought to be indispensable in the development of host anti-tumor immune responses." (PMID 31921140, 2019). "Then we tested its ability to act as an antigen carrier targeting Clec9a+ DCs both in vitro and in tumor bearing mice." (PMID 27250027, 2016). "Tumours were harvested from wild‐type (WT) mice but also from sGsn−/− mice and sGsn−/− Clec9a−/− mice to understand whether modulation of cross‐presentation in cDC1s has an impact on their cellular states." (PMID 40745918, 2025). "In several types of cancer including hepatocellular carcinoma, head and neck squamous cell carcinoma, stomach adenocarcinoma and ovarian cancer, overall patient survival appears to be favored by low levels of soluble gelsolin and higher levels of CLEC9A present in the tumor bed." (PMID 37907944, 2023). "The mouse CD8α+ Clec9a+ DCs (or stem-DCs) produced in this study demonstrated antitumor effects characterized not only by a reduced volume of ascites and number of tumor implants but also high levels of immunostimulatory cells and cytokines and low levels of immunosuppressive cytokines." (PMID 36596856, 2023). "Similarly, Clec9a-cre:Bmal1flox mice, which lack Bmal1 expression in conventional DCs (Bmal1ΔcDC), showed comparable tumour size kinetics when tumour cells were inoculated either at ZT9 or ZT21." (PMID 36470303, 2023). "We observed that CLEC9A+ cells were often typically located at the edge of tumor masses." (PMID 37526080, 2023). "The nature of tumor-infiltrating APCs may also affect the properties of T cells in tumors, as indicated by the close interactions between CLEC9A+ DCs and TCF1+ T cells that we observed." (PMID 37526080, 2023). "Therefore, we generated a second mouse model that allows the assessment of the efficacy of therapeutic vaccines delivering different human tumor antigens to human Clec9A+ DCs." (PMID 37626903, 2023). "Additionally, when Clec9a was targeted with tumor antigens and poly I:C as adjuvant, anti-tumor CD8+ T cell responses were stronger than DEC-205 targeting." (PMID 37662903, 2023). "Mature LAMP3+ DCs were transformed from CD1C+ DC and CLEC9A+ DC sub‐clusters when exposure to tumour alloantigens, which may improve T cell cytotoxicity activities on tumour cells under anti‐PD‐L1 treatments." (PMID 36305631, 2022). "The results show that targeting CLEC9A may produce a strong long-term CTL response with a significant decrease in the number of tumor cells and play an important role in inducing anti-tumor immune response and preventing tumors in the body." (PMID 36202899, 2022). "However, CBP-12 was able to deliver exogenous and endogenous tumor antigens to Clec9a and induced an antigen-specific antitumor response in the absence of an adjuvant, thus eliminating the risk of side effects associated with adjuvants." (PMID 34158852, 2021). "CLEC9A is a potential target to dendritic cell vaccines for anti-tumor use." (PMID 34616670, 2021). "Furthermore, the use of mAbs as vectors has been explored to target tumor antigens to the Clec9A DC receptor in several murine cancer models." (PMID 32075343, 2020). "Actually, Clec9a antibody conjugated with antigen could enhance the cross priming of DC cells, and simulate cytotoxic T lymphocytes (CTLs) response to elicit anti-tumor effects." (PMID 27250027, 2016). "Dendritic cells targeting antigens via CLEC9A may enhance anti-tumor immunity." (PMID 34616670, 2021). "Therefore, we studied the effect of CLEC9A on tumor immune microenvironment in LUAD." (PMID 34616670, 2021). "Importantly, targeting tumor antigens to Clec9A requires the co-administration of adjuvants, such as anti-CD40 or poly I:C, to induce effective Ag-specific CTLs; otherwise, it could result in tolerance." (PMID 32075343, 2020). "Antigen targeting DCs via Clec9a could strongly enhance anti-tumor immunity." (PMID 27250027, 2016).
tumor (continued). "Therefore, Clec9a is a very promising target to the DC vaccines for anti-tumor use." (PMID 27250027, 2016). "Intravenous Clec9A-STING liposomes stimulated IFN-dependent transcription in blood, lung, tumor, and draining lymph nodes." (PMID 42255099, 2026). "CLEC9A‐mediated targeting enhances antigen cross‐presentation via MHCI pathways and significantly improves CD8+ CTL priming in both preclinical tumor models and early‐phase clinical studies." (PMID 40667699, 2025). "In the clinic, the tumor/stroma-targeting bispecific, fibroblast activation protein (FAP)-CD40, increased DC-LAMP+ DCs and reduced CLEC9A+ DCs (cDC1) within solid tumors, with the full results yet to be published." (PMID 41086813, 2025). "cDC1s express a range of proteins that have been shown to be involved in the cross‐presentation of cellular antigens, such as DNGR‐1 (a.k.a CLEC9A) and WDFY4, both of which are crucial for anti‐tumour immunity in murine tumour models." (PMID 40745918, 2025). "In vivo, PIB adenoviruses transformed tumor cells into cDC1-like cells, which expressed immunogenic markers (MHC I/II, CLEC9A, XCR1) and attracted T cells to the TME." (PMID 39820487, 2025). "Taken together, this data suggests that FcRn plays a pivotal role in promoting the anti-tumor response elicited by DEC205 and/or Clec9A-directed DC-targeted vaccination." (PMID 38594284, 2024). "DC-targeted vaccination using mAb specific for DEC205, Clec9A and XCR1 induces cytotoxic T cell immunity that contributes to tumor eradication in prophylactic and therapeutic settings." (PMID 38594284, 2024). "Clec9a targeting was more effective than CpG ODN targeting, but the difference was less pronounced than seen in RMA-S tumor bearing mice." (PMID 38231450, 2024). "CLEC9A, (also known as DNGR1) is highly expressed on cDC1s and binds necrotic cell debris and promotes antigen processing in tumours." (PMID 35355992, 2022). "DC2s displayed decreased monocyte lineage markers and increased expression of cDC receptors, including CCR7 and Clec9a, leading to increased DC2 migration out of the tumor microenvironment." (PMID 34283809, 2021). "In comparison with DC2, DC1 uptake antigen and migrate out of the tumor with increased efficiency in accordance with their higher expression of CCR7 and Clec9a." (PMID 34283809, 2021). "Targeting CLEC9A, a CLR with advantageously restricted expression on cDC1 DCs, also elicited anti-tumor responses in multiple studies, coherent with the potent (cross-)presenting function of these DCs." (PMID 34054859, 2021). "It has been demonstrated that anti-Clec9A nanoemulsion bearing OVA or its CD8 and CD4 epitopes can efficiently induce CTL and T helper responses, as well as inhibit tumor growth in mice bearing PyMT-ChOVA breast cancer cells." (PMID 32150821, 2020). "With respect to cancer immunotherapy, the potential of antigen targeting to different endocytic receptors, including DEC205, DCIR2, CLEC9A, CD36, LOX-1, CD11c, and MHC-II was proven in several murine tumor models." (PMID 32674488, 2020). "We show here that COX2 expression at the tumor margin limits CD8+ T-cell infiltration into the tumor core, which involves at least in part reduced cytokine and chemokine expression (IRF8, CLEC9a, CXCL9, CXCL10, CXCL11, and IL27) that promotes directional immune cell migration." (PMID 39356141, 2024). "CLEC9A targeted antigen to DC may stimulate the body to produce CTL responses, identify tumor cell surface-related tumor antigens, and promote the death of tumor cells through cytotoxicity." (PMID 36202899, 2022). "Interestingly, NDV upregulated DC expression of dead-cell receptors, including Clec9A that mediates cross-presentation of dead-cell Ag32, suggesting that NDV sensitizes DCs to dying tumor cells." (PMID 36418317, 2022).
tumor (continued). "DCs were further subdivided into cDC1 (cross-presenting dendritic cells; cluster 5 in Paratumor and cluster 11 in Tumor; CLEC9A+ and XCR1+), cDC2 (cluster 1 in Paratumor and cluster 1 in Tumor; CD1C+) and plasmacytoid DC (pDC; cluster 4 in Paratumor and cluster 13 in Tumor; LILRA4+ and IL3RA+)." (PMID 33429363, 2021). "CLEC9A (also called DNGR-1) allows dendritic cells to engulf necrotic cells and then cross-present tumor-derived antigens on MHC I through a mechanism which ruptures the efferosome, thus allowing necrotic-cell antigens to be loaded onto MHC I in the endoplasmic reticulum." (PMID 34065321, 2021). "They express XCR1, TLR3 and CLEC9A and exhibit a high cross‐presentation potential of exogenous antigens through MHC class I21 hence inducing efficient CD8+ cytotoxic T‐cell responses against infected or tumor cells." (PMID 33282290, 2020). "Anti‐mouse CLEC9A Abs are as effective as anti‐mouse DEC‐205 Abs at delivering Ags to murine cDC1s in vivo to prime CD8+ T‐cell responses, as well as humoral and CD4+ T‐cell responses, which collectively mediate protective tumor‐specific immunity." (PMID 32547743, 2020). "For example, when combined with poly(I:C) and other adjuvants, Clec9a-fused antigens induce CD4- and CD8-mediated anti-tumor immunity, while fusion of human IFNα to Cle9a led to an anti-tumor response that was improved by treatment with checkpoint blockade in the murine 4T1 mammary tumor model." (PMID 32508825, 2020). "In humans, equivalent BAFT3 dependent DCs are identified by the expression of CD11c, CLEC9A, XCR1 and CD141, have been found in different tumor types and, just as the murine DC, seem to be relevant in anti-tumor responses, since their presence correlates with a superior outcome in melanoma patients." (PMID 29050360, 2017). "Moreover, it has been demonstrated that CD8α+ DCs acquire tumor antigens in vivo by recognizing and binding exposed actin filaments of necrotic cells via the receptor DNGR-1 (CLEC9A)." (PMID 26690204, 2015). "We show that CD11b+CD206+ TAM represent the dominant tumor-infiltrating myeloid cell population, expressing a unique cell surface repertoire, promoting Ag cross-presentation and Ag-specific CD8+ T cell activation comparable with cross-presenting CLEC9A+ DCs (cDC1)." (PMID 35503656, 2022). "Consequently, Ag delivery to CD1c+ DCs may further enhance tumor‐specific CD4+ T‐cell responses, even though anti‐CLEC9A and anti‐DEC‐205 Abs promote CD4+ T‐cell responses similarly after uptake by CD141+ DCs." (PMID 32547743, 2020). "Moreover, Clec9a is expressed in pDCs in mice, but reportedly not in humans, questioning whether pDCs may have contributed to the anti-tumor activity observed." (PMID 37942313, 2023). "In Clec9a-/- mice, the tumor volume was not significantly different between the CBP-12-OVA and normal saline groups, indicating that CBP-12-OVA specifically targets Clec9a in vivo and the antitumor effects are dependent on Clec9a." (PMID 34158852, 2021). "We found that the change in DC2 phenotype was not conserved outside the tumor, with only CD64 expression showing a decreasing trend while the other myeloid markers and Clec9a did not have any significant change." (PMID 34283809, 2021). "In the absence of FcRn, the ability to eradicate tumors was impaired and there was no significant reduction in tumor cell numbers when mice were immunized with DEC205-targeted OVA, while only a mild reduction in tumor load occurred in response to Clec9A-targeted OVA." (PMID 38594284, 2024).
cancer (36 papers, 2014 to 2026). A tumor composed of atypical neoplastic, often pleomorphic cells that invade other tissues. "DNGR-1 (CLEC9A), a receptor expressed by type 1 cDCs (cDC1s) and implicated in immune responses to viruses and cancer, recognises F-actin exposed on dead cell remnants and promotes cross-presentation of associated antigens." (PMID 41162754, 2025). "In regard to these results, some of the members of the C-type lectin superfamily like CLEC19A consist of CLEC10A, CLEC2, and CLEC9A suppressed cell proliferation, migration, and invasion, and also cell cycle arrest, and promoted apoptosis in cancer cells." (PMID 38167030, 2024). "This provides sufficient time to test the efficacy of immunotherapies such as cancer vaccination including those directly targeting Clec9A+ DCs in vivo." (PMID 37626903, 2023). "By strategically targeting the receptors DEC205 and Clec9A, there is a great opportunity to improve the effectiveness of cancer vaccines when administered orally." (PMID 38250839, 2023). "DEC205 and Clec9A are essential receptors found on the surfaces of dendritic cells (DCs), which are responsible for delivering cancer vaccines." (PMID 38250839, 2023). "In an in vivo cancer model, secreted gelsolin inhibits Clec9a-dependent cross presentation of antigen and dampens CD8+ T cell responses." (PMID 35173718, 2022). "MVA suppression disrupts prenylation of the small GTPase Rac1 and induces cancer cell actin filament exposure, which can be recognized by CLEC9A specifically expressed on cDC1s and thus activating infiltrating T cells." (PMID 36003368, 2022). "In cancer patients, lower expression of sGSN in the TME correlates with patient survival, especially in subcohorts of patients with increased CLEC9A intratumoral expression and prevalence of mutations in proteins associated with actin cytoskeleton." (PMID 34081922, 2021). "Most of these cancer vaccines utilize C-type lectin receptors such as DC-205 and CLEC9A for the targeted delivery of antigens to DCs including cDC1." (PMID 34065346, 2021). "In our study, antigen presentation was provided by the Clec9A+ DCs, while in the previous study, by the non‐cancer cells positive for a HY male‐specific antigen." (PMID 32704371, 2020). "Single-cell RNA sequencing has allowed for the identification of immune cell populations in cancer, both at the tumor bed and its draining lymph node, where Clec9a expression is even more restricted to cDC1s." (PMID 32117205, 2019). "Of note, a single cDC1 marker, CLEC9A, was also prognostic of patient survival and the cDC1 signature was at least as powerful a predictor of cancer patient survival as a CD8 T cell signature." (PMID 29429633, 2018). "The TLR9 ligand, CpG, has been widely used as an adjuvant in mice, including with Clec9A Ab and has been evaluated clinically, with limited adverse effects, as an adjuvant in cancer chemotherapy and ex vivo DC vaccines." (PMID 24904587, 2014). "In particular, the suppression of MVA disrupts prenylation of the small GTPase Rac1 and induces cancer cell actin filament exposure, which can be recognized by c-type lectin domain family 9 member A (CLEC9A) specifically expressed on cDC1s and thus activating infiltrating T cells." (PMID 36003368, 2022). "CLEC9A is reported to be a significant target for cancer immunotherapy." (PMID 34616670, 2021). "All these results suggested that peptide WH could be considered as an antigen delivery carrier targeting Clec9a+ DCs for cancer immunotherapy." (PMID 27250027, 2016). "However, it is the subset defined by expression of the C-type lectin-like receptor, CLEC9A, and the chemokine receptor, XCR1, that is crucial for the induction of CTL responses against cancers, viruses, and other pathogenic infections." (PMID 24904587, 2014). "Thus, expression of CLEC9A alone within resected tumors, as a marker of cDC1s, constitutes a great prognostic factor for cancer patients and could be used to select therapeutic strategies." (PMID 32117205, 2019).